EPHB2 (EPH receptor B2)
Description:
Receptor tyrosine kinase which binds promiscuously transmembrane ephrin-B family ligands residing on adjacent cells, leading to contact-dependent bidirectional signaling into neighboring cells. The signaling pathway downstream of the receptor is referred to as forward signaling while the signaling pathway downstream of the ephrin ligand is referred to as reverse signaling. Functions in axon guidance during development. Involved in the guidance of commissural axons, that form a major interhemispheric connection between the 2 temporal lobes of the cerebral cortex. Also involved in guidance of contralateral inner ear efferent growth cones at the midline and of retinal ganglion cell axons to the optic disk. In addition to axon guidance, also regulates dendritic spines development and maturation and stimulates the formation of excitatory synapses. Upon activation by EFNB1, abolishes the ARHGEF15-mediated negative regulation on excitatory synapse formation. Controls other aspects of development including angiogenesis, palate development and in inner ear development through regulation of endolymph production. Forward and reverse signaling through the EFNB2/EPHB2 complex regulate movement and adhesion of cells that tubularize the urethra and septate the cloaca. May function as a tumor suppressor. May be involved in the regulation of platelet activation and blood coagulation.
Synonyms: EK5; hEK5; DRT; EPHT3; ERK; TYRO5; BDPLT22; CAPB; PCBC
Tractability: Small molecule: an approved drug acts on it; a high-quality ligand is known; it belongs to a druggable protein family. Antibody: its Gene Ontology location is reachable by antibodies, with high confidence; UniProt places it where antibodies can reach, with medium confidence; UniProt predicts a signal peptide or a membrane-spanning region; the Human Protein Atlas places it where antibodies can reach. PROTAC: it is named in the literature on targeted protein degradation; UniProt records ubiquitination sites on it; ubiquitination databases record sites on it; its protein half-life has been measured; a small molecule that binds it is known.
Target class: Tyrosine protein kinase Eph family; Protein Kinase; TK protein kinase group; Kinase; Enzyme
Gene: Protein-coding gene on chromosome 1 (22,710,839 to 22,921,500, forward strand). Ensembl gene ENSG00000133216.
Subcellular location: Cell membrane; Cell projection, axon; Cell projection, dendrite; Secreted
Subcellular location (Human Protein Atlas): Plasma membrane; Nucleoplasm
Pathways (Reactome):
Developmental Biology: EPH-Ephrin signaling; EPH-ephrin mediated repulsion of cells; EPHB-mediated forward signaling; Ephrin signaling; L1CAM interactions
Gene Ontology:
Molecular function: protein binding; amyloid-beta binding; protein tyrosine kinase activity; protein-containing complex binding; transmembrane-ephrin receptor activity; ATP binding; axon guidance receptor activity; ephrin receptor activity; identical protein binding; protein kinase activity; signaling receptor activity; signaling receptor binding; transmembrane receptor protein tyrosine kinase activity
Biological process: B cell activation; negative regulation of cell adhesion; positive regulation of B cell proliferation; positive regulation of cell migration; positive regulation of immunoglobulin production; positive regulation of tumor necrosis factor production; regulation of blood coagulation; angiogenesis; axon guidance; axonal fasciculation; commissural neuron axon guidance; corpus callosum development; dendritic spine development; dendritic spine morphogenesis; ephrin receptor signaling pathway; inner ear morphogenesis; learning; learning or memory; negative regulation of ERK1 and ERK2 cascade; negative regulation of glutamate receptor signaling pathway; negative regulation of Ras protein signal transduction; nervous system development; neuron projection maintenance; neuron projection retraction; peptidyl-tyrosine phosphorylation; and 27 more
Cellular component: extracellular region; plasma membrane; axon; cytosol; dendrite; postsynapse; cell surface; dendritic spine; glutamatergic synapse; hippocampal mossy fiber to CA3 synapse; membrane; neuronal cell body; postsynaptic membrane; presynaptic membrane
Genetic constraint (gnomAD): Loss-of-function variants: 18 observed, 100.75 expected, observed/expected ratio (o/e) 0.18, 90% interval 0.12 to 0.26. The upper end of that interval is the gene's LOEUF score, 0.26, which puts it in group 1 of 6, group 1 being the genes least tolerant of losing a copy. Missense variants: 989 observed, 1,413.6 expected, observed/expected ratio (o/e) 0.7, 90% interval 0.66 to 0.74. Synonymous variants: 506 observed, 559.49 expected, observed/expected ratio (o/e) 0.9, 90% interval 0.84 to 0.97.
Gene-disease validity (ClinGen):
ClinGen rates the evidence that EPHB2 causes each of these diseases.
bleeding disorder, platelet-type, 22 (autosomal recessive): Limited.
Homologues: Orthologues: chimpanzee EPHB2 (99% identical), macaque EPHB2 (99% identical), pig EPHB2 (99% identical), dog EPHB2 (99% identical), mouse Ephb2 (99% identical), rat Ephb2 (99% identical), rabbit EPHB2 (97% identical), guinea pig EPHB2 (94% identical), zebrafish ephb2b (88% identical), zebrafish ephb2a (85% identical). Paralogues in human: EPHB1 (73% identical), EPHB3 (70% identical), EPHA4 (58% identical), EPHA5 (58% identical), EPHA7 (57% identical), EPHA3 (56% identical), EPHB4 (55% identical), EPHA6 (54% identical), EPHA8 (51% identical), EPHA2 (48% identical), EPHA10 (43% identical), EPHA1 (41% identical), and 41 more.
Diseases named in the same sentence as EPHB2 in open-access papers:
EPHB2 is named in the same sentence as 181 diseases in open-access papers, as found by Europe PMC text mining. Sharing a sentence is not in itself a finding about the gene and the disease. The quoted sentences say what the papers report.
colorectal cancer (39 papers, 2006 to 2025). A primary or metastatic malignant neoplasm that affects the colon or rectum. "The expression of EphB2 is also downregulated by undetermined factors; hence, the repulsive Eph-ephrin interaction is fully lost, leading to obesity-associated colorectal cancer progression." (PMID 35949596, 2022). "EphB2 downregulation has been associated with poor prognosis in various human cancers, including colorectal cancer." (PMID 35949596, 2022). "It has been reported that mutations in repetitive sequences in the exon 17 of EphB2 are frequent in colon adenomas and colorectal carcinomas." (PMID 35949596, 2022). "As in the case of EphA1 and EphA2, initial upregulation of EphB2 and EphB3 expression appears to be followed by a loss of expression in the more advanced metastatic stages of colorectal cancer." (PMID 33430066, 2021). "A higher level of EphB2 protein expression is associated with better clinical outcomes including both overall and recurrence-free survival of patients with colorectal cancer." (PMID 32226496, 2020). "The EphB2 gene has been implicated as a tumor suppressor gene somatically altered in both prostate cancer (PC) and colorectal cancer." (PMID 21603658, 2011). "We screened for germline EPHB2 sequence variants in 116 population-based familial colorectal cancer cases by DNA sequencing." (PMID 18682749, 2008). "Our findings suggest that rare EPHB2 alleles contribute to a small fraction of familial colorectal cancer." (PMID 18682749, 2008). "In summary, we identified a germline EPHB2 variant (G787R) with diminished biological activity in a colorectal cancer patient, and suggest that EPHB2 mutations contribute to a small fraction of hereditary colorectal cancer." (PMID 18682749, 2008). "There have been two other investigations examining the contribution of germline EPHB2 mutations to colorectal cancer susceptibility." (PMID 18682749, 2008). "Tumor tissue from the G787R variant case manifested loss of heterozygosity, with loss of the wild-type allele, supporting a tumor suppressor role for EPHB2 in rare colorectal cancer cases." (PMID 18682749, 2008). "In the current study, we screened 116 population-based familial cases of colorectal cancer for mutations in a candidate tumor suppressor gene, EPHB2, and identified three candidate variants (A438T, D679N, G787R), which were further characterized." (PMID 18682749, 2008). "We also screened for EPHB2 mutations in 10 colorectal cancer cell lines, and Caco2 was found to express a novel variant, R4Q (nt." (PMID 18682749, 2008). "Genotyping of additional patients with colorectal cancer and control subjects revealed that A438T and G787R represent rare EPHB2 alleles." (PMID 18682749, 2008). "In addition, high levels of EphB2 expression were found to be associated with a longer mean duration of survival in colorectal cancer, and a loss of EphB2 expression has been reported in colorectal tumors." (PMID 38391938, 2024). "Anti-inflammatory therapy targeting macrophage infiltration or inhibiting the silencing of EphB2 may offer novel approaches for inhibiting obesity-associated colorectal cancer development and progression." (PMID 35949596, 2022). "Therefore, in this study, we screened 116 population-based familial colorectal cancer cases for germline EPHB2 mutations." (PMID 18682749, 2008). "EPHB2 has recently been implicated as a candidate tumor suppressor gene in colorectal cancer." (PMID 18682749, 2008). "However, subsequent analysis of additional subjects suggests that D679N represents a rare neutral EPHB2 polymorphism, since the variant allele was observed at similar frequencies in patients with colorectal cancer (11 out of 1133) and population-matched controls (11 out of 1160)." (PMID 18682749, 2008). "Silencing of EphA1 and EphB2 was shown to block autophagy and cell death in colorectal cancer cells." (PMID 38391938, 2024).
colorectal cancer (continued). "In particular, the downregulation of EPHB2 and LEFTY1 and upregulation of NUPR1 genes known to be associated with colorectal cancer were observed, suggesting their involvement in tumorigenic microenvironment." (PMID 39285481, 2024). "Eph receptor B2 (EphB2), an important member of the Eph receptor family, has been demonstrated to be aberrantly expressed in many cancer types, including colorectal cancer, gastric cancer, and HCC, where it results in tumor occurrence and progression." (PMID 36980210, 2023). "EPHB2 is highly expressed in colorectal cancer and inhibits the growth, adhesion and migration of colon cancer cells." (PMID 37023088, 2023). "Taken together, these studies suggest that obesity results in EphB2 downregulation in colorectal cancer by promoting the methylation of its promoter." (PMID 35949596, 2022). "EPHB2, a receptor tyrosine kinase, promotes tumor progression in glioblastoma, colorectal cancer, and hepatocellular carcinoma." (PMID 36159187, 2022). "On the contrary, in colorectal cancer and bladder cancer, EphB2 functions as a tumor suppressor and its expression level is reduced." (PMID 35223830, 2022). "Eph receptor B2 (EphB2), an important member of the Eph receptor family, has been proved to be aberrantly expressed in many cancer types, such as colorectal cancer, gastric cancer and hepatocellular carcinoma, resulting in tumor occurrence and progression." (PMID 35223830, 2022). "The findings suggested that obesity results in disruption of EphB2/ephrin-B1 signalling, promoting colorectal cancer development and progression." (PMID 35949596, 2022). "Previous work has indicated EphB2 as a surface marker for stem-like tumor cells with robust tumor-initiating capacity and long-term self-renewal potential in human colorectal cancer." (PMID 34621019, 2021). "A large number of studies have demonstrated the independent prognostic significance of EPHB2 expression in multiple malignancies, such as colorectal cancer, breast cancer, gastric cancer and rectal cancer." (PMID 34419075, 2021). "EphrinB2 (EPHB2) expression in a mouse model of colorectal cancer is subject to competing positive regulation by Tcf7l2 and negative regulation by Lef1." (PMID 32403323, 2020). "Overall, these results indicate that colorectal cancer is distinct from other cancer types in displaying higher expression of EphrinB2 and its receptors EphB1, EphB2, EphB3, and EphB4." (PMID 31545551, 2019). "We extended analysis of the effects of NVP and NVP‐Iso on cell proliferation to include the 10 colorectal carcinomas cell lines in which the silencing EphrinB2, EphB2, or EphB4 significantly reduced cell proliferation." (PMID 31545551, 2019). "The results show that NVP and NVP‐Iso were significantly less effective at reducing the proliferation of HT‐29 and SW620 colorectal carcinoma cells after EphB2 (sh424) and EphB4 (sh774) were both silenced compared to the control cells." (PMID 31545551, 2019). "We examined the expression of EphrinB2 ligand and the EphrinB2 signaling receptors (EphB1, EphB2, EphB3, EphB4, and EphA4) in colorectal carcinoma." (PMID 31545551, 2019). "EphB2 and EphA2 control stemness and differentiation in the intestinal mucosa, but the way they cooperate with the complex mechanisms underlying tumor heterogeneity and how they affect the therapeutic outcome in colorectal cancer (CRC) patients, remain unclear." (PMID 30501625, 2018). "The altered expressions of EphB2 and EphB4 in colorectal cancer have been explained by changes in adenomatous polyposis coli (APC) suppressor gene activity, CBP complex, and Wnt pathway." (PMID 29682554, 2018). "Overexpression of EphA4 gene and reduced EphB2 gene expression correlate with liver metastasis in colorectal cancer." (PMID 27487126, 2017). "A similar pattern of expression has been observed in colorectal cancers using EPHB2 and cytokeratin 20 as a differentiation marker." (PMID 26367378, 2015).
colorectal cancer (continued). "Taken together, these data demonstrate that ERBB3+ colorectal cancer cells are predominantly non proliferative and differentiated, in contrast to EPHB2+ cells." (PMID 26367378, 2015). "Colorectal cancer patients with high expression of an intestinal stem cell gene signature, including LGR5 and EPHB2, have a 10-times higher risk of relapse compared to patients with low levels." (PMID 26367378, 2015). "Non-synonymous germline EPHB2 missense changes identified in familial and random colorectal cancer cases." (PMID 18682749, 2008). "Ephrin receptor B2 (EPHB2) has recently been proposed as a novel tumor suppressor gene in colorectal cancer (CRC)." (PMID 16740153, 2006). "Recent findings have demonstrated that EPHB2 appears to have a role in tumor progression, and acts as a tumor suppressor gene in colorectal cancer." (PMID 16740153, 2006). "For example, in colorectal cancer, EPHB2 often exhibits a tumor-suppressive role, and its inactivation correlates with tumor progression and invasion; whereas in prostate cancer, EPHB2 may promote tumor growth and metastasis." (PMID 41322437, 2025). "However, the expression of EphB2 is low in other tumors, such as colorectal cancer and bladder cancer, indicating that it exerts a tumor-suppression effect." (PMID 35223830, 2022). "Finally, our investigations focused on EphB2 and ephrin-B1 expression in colorectal cancer; however, other ephrins, including Eph-B3 and Eph-B4, have also been implicated in colorectal carcinogenesis." (PMID 35949596, 2022). "However, EphB2/ephrin signaling was able to suppress colorectal cancer expansion and invasion via repulsive mechanisms." (PMID 35223830, 2022). "Thus, EphrinB2 and its receptors EphB2 and EphB4 are general regulators of colorectal carcinoma cell proliferation/viability." (PMID 31545551, 2019). "The relationship of elevated expression of EphB2 and EphB3 with abnormal migration of epithelial cells in the crypt villus junction in colon tumors of mice is suggestive of Eph receptor involvement in colorectal cancer." (PMID 29682554, 2018). "In contrast, c-Rel as a homo-dimer or in association with p50 and p65, repress transcriptional activation by NFκB19 and c-Rel has been previously shown to be a repressor of certain gene promoters in human cells, such as Ephrin type-B receptor 2 (EPHB2) in colorectal cancer cells." (PMID 28533548, 2017). "Our results show that most colorectal cancers we examined resemble normal tissue with distinct cell compartments and proliferative status and that a dual EPHB2/ERBB3 signature could identify tumours with this morphology." (PMID 26367378, 2015). "Furthermore, somatic alterations at the EphB2 locus have been reported in colorectal cancer as well, further supporting a role for EphB2 as an important cancer gene." (PMID 21603658, 2011). "However, since only 50 samples of likely sporadic cases of colorectal cancer were analyzed, a tumor suppressor role for EPHB2 cannot be excluded." (PMID 18682749, 2008). "Despite study design differences, together these three investigations suggest that EPHB2 germline mutations are not common occurrences in colorectal cancer." (PMID 18682749, 2008). "In contrast to these two earlier reports, our study was designed to specifically evaluate the role of germline EPHB2 mutations in patients with familial colorectal cancer, and not in sporadic cases." (PMID 18682749, 2008). "Observed EPHB2 germline variations in colorectal cancer and hyperplastic polyposis patients." (PMID 16740153, 2006). "However, EphB2 expression was decreased in colorectal cancer (CRC)." (PMID 35223830, 2022). "In addition, hypermethylation of EphB2 promoter is frequently found in colorectal cancer patients." (PMID 35949596, 2022). "However, the association of EPHB2 was not studied in cervical cancer; instead, its down-regulation was reported in colorectal cancer." (PMID 30020984, 2018). "Interestingly, most MUC2+ colorectal cancer cells were also EPHB2-/ERBB3+." (PMID 26367378, 2015).